IL10 (interleukin 10)
Diseases named in the same sentence as IL10 in open-access papers (continued):
Sharing a sentence is not in itself a finding about the gene and the disease.
malaria (continued). "It is hypothesized that the T allele and TT genotype may increase the production of IL10 and severe malaria." (PMID 34698295, 2021). "Taken together, Ferritin, IL-6 and IL-10 could play significant roles in the inflammatory processes, severe anemia and pathologies associated with malaria." (PMID 35223394, 2021). "Furthermore, high TNF-α/IL-10 ratio has also been associated with anaemia due to malaria in an earlier study." (PMID 34426742, 2021). "In addition, a significant association was found between IL10 -1082A and decreased IL10 production in severe malaria." (PMID 34698295, 2021). "In contrast to the protection against clinical malaria associated with this type of IL10-producing CD4+ T cells, protection against infection was governed by a different CD4 response profile, but both types of protection are considered part of the naturally acquired immunity against malaria." (PMID 34684226, 2021). "In addition, a number of studies have reported associations between IL-10 SNPs and susceptibility to malaria with either protective effects in some SNPs and increased susceptibility in others." (PMID 33593344, 2021). "In addition, microarray studies have shown that recent and heavy exposure to malaria is associated with a loss of proinflammatory cytokine production, and higher levels of the anti-inflammatory cytokine interleukin 10 (IL-10)." (PMID 32636334, 2020). "However, a low IL-10 to TNF-α ratio is associated with enhanced severity to malaria anemia and reduced serum IL-10 was observed in pediatric patients from Ghana with SMA." (PMID 32373101, 2020). "High TNF-α/IL-10 ratio has also been associated with anaemia due to malaria in an earlier study." (PMID 33195706, 2020). "In addition, previous studies have associated asymptomatic malaria with relatively decreased levels of pro-inflammatory responses, relative to the regulatory cytokine IL-10." (PMID 33281757, 2020). "Although IL-10 is associated with parasite persistence and dissemination, it is also important for controlling the exaggerated inflammatory response associated with pathology observed in parasitic diseases such as malaria, Chagas disease, and leishmaniasis." (PMID 31119102, 2019). "Likewise, although significant associations were seen between severe malaria and polymorphisms in seven additional genes (IL10, LPHN2 [ADGRL2], LOC727982, ARL14, RPS6KL1, CAND1, and GNAS), without further data their potential for translation remains elusive." (PMID 30033078, 2018). "Increased levels of IFN-γ, TNF-α, IL-12 and IL-10 are known to be associated with a reduced risk of malaria; however, those who become infected with malaria parasites have an elevated risk of symptomatic malaria." (PMID 29970128, 2018). "High ratios of TNFα to IL-10 have also been linked to severe malaria in children from this region." (PMID 28337195, 2017). "The total IL10 response and frequency of IFNγ/IL10 coproducing cells, but not IL10 single-producing cells, were weakly associated with malaria incidence in the preceding year (rho = 0.14, p = 0.02, rho = 0.16, p = 0.01 and rho = 0.026, p = 0.67, respectively), consistent with prior reports." (PMID 29097996, 2017). "Furthermore, higher number of previous malaria episodes was associated with higher IL-10 plasma levels (p < 0.0242)." (PMID 28118834, 2017). "In our cohort, it was specifically monofunctional IL10 CD4 T cells that were associated with a reduced risk of symptomatic malaria following Pf infection; high frequencies of these cells were significantly associated with reduced odds of symptomatic malaria when infection." (PMID 29097996, 2017). "We identified an important transcriptional regulator called B lymphocyte-induced maturation protein 1 (Blimp-1), which promotes IL-10 production by IFNγ-producing CD4+ T (Tr1) cells during malaria and visceral leishmaniasis, two important diseases caused by protozoan parasites." (PMID 26765224, 2016).
malaria (continued). "This implies that the susceptibility to symptomatic malaria in pregnancy may be associated with high levels of IL-10." (PMID 27796349, 2016). "The immune response underlying malaria-related jaundice, which is defined by high productions of interleukin (IL)-6, IL-10 and interferon (IFN)-γ, may influence hepcidin levels in hepatocytes and peripheral blood mononuclear cells." (PMID 26466783, 2015). "Therefore, this study examined the SNPs polymorphisms that affect the expression of genes encoding IFN-γ (−874 T/A), IL-10 (−1082A/G, −819 T/C and -592A/C) and iNOS (−954G/C) from a Brazilian Amazonian population living in malaria endemic area of Brazil." (PMID 25627396, 2015). "Thus, IL-10 produced during the immune response to malaria increases susceptibility to disseminated NTS infection by suppressing the ability of myeloid cells, most likely macrophages, to control bacterial infection." (PMID 24787713, 2014). "We hypothesized that CD4+ T cells producing the pro-inflammatory cytokines IFNγ and/or TNFα are associated with protection from malaria, and that T cell production of the regulatory cytokine IL-10 may interfere with the acquisition of protection." (PMID 24415936, 2014). "However many protozoan parasites, such as those that cause toxoplasmosis, malaria, trypanosomiasis, and leishmaniasis, have evolved to exploit the functions of IL-10 to inhibit anti-microbial mechanisms and allow the establishment of chronic infection." (PMID 25352846, 2014). "Indeed, polymorphisms in genes encoding IL-10 have been associated with susceptibility to malaria, although their functional role in severe malaria still remains open to question." (PMID 24934404, 2014). "Thus, in murine malaria models, production of IL-10 serves to limit damage caused by the inflammatory response to malaria parasites." (PMID 24787713, 2014). "IL-10 may be increased in severe malaria while low IL-12 was also reported to be associated with increased malaria disease severity in children." (PMID 24669217, 2014). "To determine the importance of macrophage IL-10 production for malaria-mediated susceptibility to disseminated infection, we bred mice that were conditionally deficient for IL-10 production by cells of the myeloid lineage, which includes neutrophils and monocytes/macrophages." (PMID 24787713, 2014). "Indeed, high levels of IFN-γ associated with low levels of IL-10 have been associated with the severe form of malaria caused by P. vivax." (PMID 24741587, 2014). "In univariate Cox proportional hazards analysis evaluating time to next episode of malaria, a higher frequency of CD4+ T cells producing any IFNγ or IL10, or the combinations IFNγ+/IL-10+/TNFα− and IFNγ−/IL-10+/TNFα− was associated with a significantly increased hazard of malaria (left columns)." (PMID 24415936, 2014). "Other studies indicate that IL-10 were associated with Th2 response during malaria." (PMID 24359168, 2013). "Therefore, the aim of this study was to investigate the expression of ANXA1 in CD4+, CD8+ T cells, regulatory T cells (Treg) and quantification of the cytokine IL-10 in plasma from patients with malaria caused by P. vivax." (PMID 24359168, 2013). "The association of IL10 with severe malaria might be confounded by foetal survival rates or other sources of transmission bias, since genetic variation at the IL10 locus has been implicated as a determinant of fertility." (PMID 24312262, 2013). "Furthermore, high IL-10 levels predicted P. falciparum infection during pregnancy in Tanzanian women, and increased IL-10 levels were associated with asymptomatic malaria in pregnant women from Ghana." (PMID 24180253, 2013). "In addition to age, plasma IL-10 levels were also associated with having had previous episodes of clinical malaria (proportional difference = 1.45 [1.14-1.86], P = 0.0028) and having current infection (proportional difference = 1.80 [1.41-2.29], P < 0.0001)." (PMID 22280502, 2012).
malaria (continued). "The altered lower features of NF-κB p65 in the PBMCs of patients with complicated P. falciparum at admission could be due to a suppressive effect of high IL-10 associated with complicated P. falciparum malaria." (PMID 22682094, 2012). "The results suggest a need for associations studies with more dense mapping of candidate genes, especially CTL4 and IL-10, along with other genes from the major histocompatibility complex region to identify additional functional variants most relevant for malaria in Amazonian populations." (PMID 22615793, 2012). "Notably, HBV malaria co-infection was associated with reduced values of IFN-γ/IL-10 ratios (P<0.0001, compared with HBV mono-infection)." (PMID 21625634, 2011). "IL-10 responses have been linked to human resistance to malaria." (PMID 21625634, 2011). "Previous episodes of malaria during infancy showed weaker effects, but a high number of episodes was associated with a reduced IL-5 response to cCFP (aGMR 0.84 (0.76, 0.95)) and an increased IL-10 response to TT (aGMR 1.18 (1.03, 1.34))." (PMID 21040693, 2010). "Both increased and decreased levels of IL-10 have been associated with poor malaria outcomes." (PMID 18230163, 2008). "However, the IL10 rs3024500 SNP has been found to increase the risk for severe forms of malaria." (PMID 38404582, 2024). "In addition, anti-inflammatory cytokines, e.g. IL-10, were found to protect against malaria-associated immunopathology, but may in parallel aggravate infection by inhibiting anti-parasitic pro-inflammatory responses." (PMID 39355242, 2024). "Moreover, repeated malaria exposures are associated with a modified immune system in children that is marked by upregulation of interferon-inducible genes, higher levels of IL-10 and enhanced cellular activation and have also been associated with immunosuppression and immune cell exhaustion." (PMID 38274822, 2023). "Therefore, the pathogenesis of severe malaria with different clinical complications may cause distinct forms of IL-10 alterations." (PMID 36668942, 2023). "Although IL-10 is related to parasite persistence and dissemination and MΦ-M2 polarization, it is also a key cytokine for controlling the exaggeration of the inflammatory response associated with pathology present in parasitic diseases such as malaria, Chagas disease, and leishmaniasis." (PMID 37190011, 2023). "Therefore, the distinct regulatory role of the IL-10 levels in malaria may be linked with the age of the participants, areas with different transmission intensities, and Plasmodium spp." (PMID 36668942, 2023). "Indeed, mice with a T cell-targeted IL-10 deficiency are susceptible to greater disease severity following Plasmodium infection, and we previously reported that nnCD4+ production of IL-10 was associated with decreased disease severity in malaria-exposed children." (PMID 37634385, 2023). "On the other hand, symptomatic malaria occurs during the blood stages when merozoites are released in the bloodstream and results in a cascade of inflammatory cytokines such as IL-6, IL-8, IL-10, IL-1, and IL-12 that are associated with a “cytokine storm” that is implicated in disease severity." (PMID 36415655, 2022). "Modulation of IgG and IL-10 levels could impair monocyte functions (opsonisation/phagocytosis) in infants born to women with PM, possibly contributing to their higher susceptibility to malaria." (PMID 35911674, 2022). "In another study with children living in a holo-endemic area of Western Kenya, higher ratios of plasma IL-10 to TNF levels were strongly associated with protection against severe malaria anemia, providing evidence that IL-10 may be protective by inhibiting TNF activity." (PMID 30809232, 2019). "Thus, the diminished peripheral levels of IL-10 and IL-4 in the women with Malaria+CHB may suggest susceptibility to cytokine imbalance (towards Th1)." (PMID 31002731, 2019).
malaria (continued). "This study shows that the IL10A-592A/C and IL10A-819 T/C polymorphisms were associated with malaria and decreased IL-10 levels and low parasite density suggesting that this polymorphism influence IL-10 levels and may influence in the susceptibility to clinical malaria." (PMID 25627396, 2015). "The IL10A-592A/C and IL10A-819 T/C polymorphisms were associated with malaria and decreased IL-10 levels and low parasite density suggesting that this polymorphism influence IL-10 levels and may influence in the susceptibility to clinical malaria in Amazonian population." (PMID 25627396, 2015). "However, the association between HbS rs334 and ADCY9 rs2230739 with plasma levels of transforming growth factor-beta as well as ABO rs8176746 with interleukin-10 is quite interesting since resistance to severe malaria has been linked to the ability to produce these immuno-regulatory cytokines." (PMID 24934404, 2014). "Mice that were conditionally deficient for either myeloid cell IL-10 production or myeloid cell expression of IL-10 receptor were better able to control systemic Salmonella infection, suggesting that phagocytic cells are both producers and targets of malaria parasite-induced IL-10." (PMID 24787713, 2014). "Therefore, screening of further case–control groups would be useful to explore whether IL10 variants are involved in malaria susceptibility in other Sub-Saharan African populations." (PMID 24312262, 2013). "Thus, susceptibility to symptomatic malaria in pregnancy may be associated with high levels of IL-10 and G-CSF and dysregulation of pro and anti-inflammatory factors in pregnant women." (PMID 20706538, 2010). "In addition, studies in murine models of malaria have suggested that IL-10 response during infection may be associated with the disease exacerbation." (PMID 20706538, 2010). "IL-10 is well-established as a vital homeostatic regulator of malaria-induced inflammation that prevents immune-pathology in mice, promotes the necessary switch from early Th1 to subsequent Th2 responses, and has been linked to protection from severe malaria anaemia, and death in humans." (PMID 19343213, 2009). "However, the role that IL-10 plays may depend on its levels, since very high levels of IL-10 have been associated with severe malaria in humans and some animal models." (PMID 17997848, 2007). "A strong positive correlation was observed between IFN-γ and IL-10 (rho = 0.688, p < 0.001) in malaria patients." (PMID 42194890, 2026). "On the contrary, the level of IL-1β was significantly lower in the malaria group with a higher level of IL-10." (PMID 40014608, 2025). "We tested our approach on Maf, a gene that promotes Tfh-differentiation during immunization, and IL-10 production in malaria, but whose role in Tfh-differentiation during Plasmodium infection remains to be formally demonstrated." (PMID 40132035, 2025). "As an important component of this regulation, IL-10 suppresses inflammation during malaria and other infections by dampening the production of proinflammatory cytokines, downregulating MHC-II on antigen presenting cells, and promoting humoral immunity." (PMID 40337867, 2025). "These malaria-specific Tr1 cells seem to be the engine of IL-10 production in human disease and, in addition to IL-10, express large quantities of IFNγ, making them ideal for both reducing inflammation, via IL-10, and suppressing parasitemia." (PMID 40972121, 2025). "Among the patient groups, the mean IL-2/IL-10 ratio was significantly higher in typho-malaria group compared to the malaria group (p = 0.0067)." (PMID 40014608, 2025). "Greater IL-10 secretion from the NK cells of malaria-exposed individuals along with evidence of enhanced cytotoxicity and activation of these cells imply a dual role for NK cells as both important for parasite clearance and immunoregulation." (PMID 40337867, 2025).
malaria (continued). "Surprisingly, about 20-fold more NK cells from malaria-experienced individuals secreted IL-10 as compared with malaria-naive controls." (PMID 40337867, 2025). "In spite the insignificant variation among patient groups, the malaria group showed a very strong significant rise in IL-10 (p = 0.0006) compared to the heathy control." (PMID 40014608, 2025). "We found that individuals with malaria experience had a significantly higher proportion of NK cells producing IL-10 relative to malaria-naive individuals." (PMID 40337867, 2025). "NK cells from individuals in malaria-endemic regions secrete more IL-10 than NK cells from malaria-naive individuals." (PMID 40337867, 2025). "Taken together, these data indicate that the NK cells from malaria-experienced individuals more robustly secrete IL-10 compared with those from malaria-naive individuals." (PMID 40337867, 2025). "This was also observed in multiple publications that show that CD4+ T cells in malaria-experienced children were concurrently producing IL-10 and IFN-γ." (PMID 40337867, 2025). "There is evidence that subclinical malaria results from an increase in levels of both anti-inflammatory and pro-inflammatory cytokines, including IL-10." (PMID 40972121, 2025). "Natural kill cell immunosuppressive IL-10 production signature where IL-10 is significantly increased in malaria experienced individuals." (PMID 40337867, 2025). "While IL-6 concentrations were significantly higher in malaria and typho-malaria co-infected patients, IL-10 levels were reduced in the typho-malaria group but remained elevated compared to controls." (PMID 40014608, 2025). "In severe malaria, dysregulation of inflammatory mediators, such as IL‐12, IL‐10, TNF‐α, PGE2, and NO, occurs, impacting cytokine production and effector molecule balance." (PMID 41171200, 2025). "More importantly, we observed significantly higher IL-6 and IL-10 levels among individuals with previous malaria." (PMID 40726977, 2025). "NK cells from malaria-naive individuals were also incubated with IL-15 and IL-21 for 6 days, where the proportion of IL-10 production is approximately 2%." (PMID 40337867, 2025). "High circulating levels of IL-10 have been reported in patients with severe malaria as well as individuals with repeated but more moderately symptomatic disease." (PMID 40972121, 2025). "Previous studies have also shown that CD4+ T cells from individuals in malaria-endemic areas also display a marked increase in IL-10, which was dependent on malaria infection experience." (PMID 40337867, 2025). "A previous study had shown that Maf is required for Tr1 cells to express the immune-suppressive cytokine, interleukin-10, in malaria." (PMID 40132035, 2025). "On the other hand, IL-10 levels were slightly reduced in the typho-malaria group (255.3 ± 177.0) compared to the mono- malaria (293.1 ± 106.8) and typhoid fever (2262.6 ± 131.9) groups, but significantly higher when compared with control (130.9 ± 51.56)." (PMID 40014608, 2025). "IL-10 positive Tr1 cells have been identified in patients with seasonal malaria; based on our animal data, we predict these cells will be an important element of chronic subclinical malaria in hyperendemic regions of the world." (PMID 40972121, 2025). "To discover extracellular markers that correlate with IL-10 release in an unbiased manner, we utilized a 350-marker flow cytometry screening panel and single-cell RNA-Seq to analyze cytokine stimulated malaria-naive NK cells." (PMID 40337867, 2025). "Accordingly, the exact role of IL-10 in preventing the sequelae of malaria is unclear as it is expressed under virtually every circumstance of infection." (PMID 40972121, 2025). "Overall, there was a relatively stable frequency of NK cells producing IL-10 before, during, and after an individual presented with clinical malaria." (PMID 40337867, 2025).